CD4 (CD4 molecule)
Diseases named in the same sentence as CD4 in open-access papers (continued):
Sharing a sentence is not in itself a finding about the gene and the disease.
tumor (continued). "More TIM-3-PD-1+ CD4+ T cells in the tumor support the notion of an increased population of exhausted T cells capable of reinvigoration." (PMID 36419897, 2022). "In CLL, a tumor-supportive role of TIGIT+CD4+ T cells was observed in the presence of TIGIT-Fc via down-regulation of IFNγ and IL-10 production." (PMID 35656508, 2022). "Th1-dominant CD4+ T cells induced by cryo-thermal therapy inhibited the tumor growth, enhanced the cytotoxicity of CD8+ T and NK cells, promoted the maturation of APCs and MDSCs, and decreased the levels of Tregs and MDSCs to maintain antitumor immune memory." (PMID 35874660, 2022). "For example, a combination of costimulatory agonists anti-OX40 and anti-4-1BB mAbs with vaccine, in a breast Her-2/neu transgenic mouse model, enhanced both CD4+ and CD8+ T cell activity and proliferation associated with the retardation of tumor growth." (PMID 36159809, 2022). "Previous studies confirm that enrichment of CD4+ and CD8+ T cells and high expression of immune checkpoint genes in tumor tissues are generally associated with a good response to anti-PD-1/PD-L1 therapy." (PMID 36386817, 2022). "Our model also highlights the potential role of CD4+ naive T-cells in tumor microenvironment in promoting irAEs developement." (PMID 36505471, 2022). "Tumor-derived CD4+ effector memory T cells expressed high levels of PD-1 and were functionally exhausted after interaction with-MDSCs." (PMID 36140392, 2022). "Memory CD4+ T cells, meantime, suppress the expansion of tumor cells by encouraging the multiplication of CD8+ cells." (PMID 36164348, 2022). "One of the challenges for CD4+ TCR-T therapy resulted from the rare expression of MHC class II molecules on most tumor cells." (PMID 35928827, 2022). "Tumor-specific antigen (TSA) can activate highly specific CD8+ T cells CD4+ T cells and tumor-specific antibodies." (PMID 36209263, 2022). "Here, we identified a novel anti-OX40 agonistic antibody DF004, which stimulated the proliferation of human CD4+ T cells in vitro and inhibited tumor growth in a mouse model." (PMID 36139048, 2022). "These TDO2+ myofibroblasts were located distally from tumor nests, and both CD4+ and CD8+ T cells were enriched around them." (PMID 35972800, 2022). "First, PHLDA1 was positively correlated with the infiltration levels of a variety of immunocompetent tumor-infiltrating cells, including Act CD4, CD56dim, and Act DC, and 23 types of immune promoters, including IL6, NT5E, and TNFSF9." (PMID 36142223, 2022). "Subclusters with Entpd1 expression were assigned as tumor-specific T cells, including Treg (CD4+Foxp3+), CD8+ effector (Gzmb+Prf1+Ifng+), CD8+ effector memory (Cd44+Cd69+), CD8+ exhausted subclusters (Pdcd1+Lag3+Tigit+Havcr2+)." (PMID 36209176, 2022). "A cell neighborhood coordination analysis also showed that the cluster of exhausted CD8+ TILs (cluster 33) strongly interacts with two tumor cell clusters (clusters 28 and 32) as well as a cluster of CD4+ TILs (cluster 21)." (PMID 36376874, 2022). "Treg cells are an important subtype of CD4+ helper T cells that can suppress antitumor immune responses and promote tumor progression." (PMID 36330441, 2022). "We found the same tendency in the amount of EBV genetic material detected in the tumor and lymph node samples, as well as in the level of PD-1 expression on CD4+ and CD8+ T cells in all the samples." (PMID 35158748, 2022). "Preclinical studies have revealed that histone deacetylase (HDAC) inhibitors modulate the activation state of the APCs to effectively prime naive Ag-specific CD4+ T cells and restore the responsiveness of tolerant T cells isolated from tumor-bearing mice." (PMID 35058524, 2022). "An analysis of paired pre- and post-NACT tumor samples from 60 patients with gastric cancer revealed that, whereas the expression of Foxp3 remained unchanged, the expression of CD4, CD8, PD-1, PD-L1, and TIM3 increased dramatically after NACT." (PMID 36439457, 2022).
tumor (continued). "During tumor immunity, the function of helper CD4+ T cells is weakened, while the immunosuppressive function of regulatory T cells is enhanced." (PMID 35445056, 2022). "In UDCA-treated LLC tumor-bearing mice, a decrease in CD4+ CD25+ Foxp3+ Treg cells among tumor-infiltrating leukocytes (TILs) was observed." (PMID 35701426, 2022). "Downregulation of MIF in BC is associated with a significant increase in infiltration and anti-tumor functions of CD4+ and CD8+ T cells." (PMID 35842634, 2022). "It was confirmed that TS played an anti-tumor role by regulating T cells, though this effect is even more pronounced for the regulation of CD4+ T cells." (PMID 35577774, 2022). "CD4+ T cells can affect tumor growth either directly or indirectly by secreting a variety of cytokines." (PMID 35814662, 2022). "The TME of solid tumours contains a variety of immune cells, such as CD8+ T cells, CD4+ T cells, natural killer cells (NKs), and dendritic cells (DCs), which act as anti-tumour agents." (PMID 36405713, 2022). "T cells were mainly found in the tumor stroma with very few cells infiltrating tumor epithelial nests with a median of 19 and 11 cells/mm2 for CD4+ and CD8+ T cells, respectively." (PMID 35954489, 2022). "On the other hand, selective loading of exosomes with tumor-suppressive miRNAs, such as miR-124 seems to regulate immune responses from CD4 and CD8 T cells, leading to enhanced immunotherapeutic efficacy." (PMID 35163397, 2022). "Nonetheless, we detected significant increases in tumor-infiltrating inflammatory monocytes, DCs, and CD4+ T cells in MB49 EV-primed animals." (PMID 35328324, 2022). "Central memory CD4+ T cells were reported to have stronger anti-tumor capacity compared with that of effector memory CD4+ T cells." (PMID 35222534, 2022). "Previous studies have shown that IDO1 and 2 can suppress anti-tumor immune response by activating CD4+CD25+Foxp3+ regulatory T cells (Treg) and myeloid-derived suppressor cells (MDSCs), which consequently inactivate CTLs." (PMID 35656514, 2022). "In the tumor microenvironment, CD4+ T cells have been shown to have a role in tumor invasion and advancement." (PMID 36059798, 2022). "In particular, immune responses induced by a DC–tumor hybrid were dependent on CD4+ and CD8+ T cells." (PMID 35806328, 2022). "The changing pattern of the CD4_c5 subcluster occurred in parallel with that of the CD8+ TRM and TEM subclusters, suggesting an anti-tumor role of these CD4+ cells." (PMID 35316682, 2022). "Tregs can inhibit anti-tumor immunity, DC antigen presentation and CD4+ T helper (Th) cell function." (PMID 35541908, 2022). "It has also been shown that B cells play a role in TME by inhibiting tumors, such as B cells and CD4 + T follicular helper cells collaborating to promote anti-tumor CD8 + T cell responses." (PMID 36147461, 2022). "It is suggested that tumor-infiltrating CD4+ and CD8+ T cells are reduced in old mice compared to young mice and old mice are more infiltrated with neutrophils and macrophages." (PMID 36299414, 2022). "The CD4+ can activate other lymphocyte subsets by releasing cytokines and suppress tumor development by directly killing tumor cells that express adequate levels of major histocompatibility complex (MHC) class II molecules." (PMID 36051923, 2022). "Several types of immune cells, such as the central memory CD4 T-cell, central memory CD8 T-cell, and effector memory CD8 T-cell, were found significantly less recruited in high-risk group tumor environment." (PMID 36685892, 2022). "This stage is crucial in the elimination of tumor cells through FasL-Fas interaction by CD4 lymphocytes." (PMID 35628562, 2022). "The amount and TCR repertoire ITH of CD4+ and CD8+ TILs and mean clonality of CD8+ TILs in tumor centers were associated with relapse in lung adenocarcinoma patients, suggesting potential clinical significance of TCR repertoire." (PMID 36476317, 2022).
tumor (continued). "The 10-fold upregulation of IL17A alludes to the role of IL-17-producing CD4+ T cells (Th17 cells) during tumor development, which drive tumorigenesis." (PMID 35356003, 2022). "Blocking naive CD4+ T cells from entering into breast cancer tumors also significantly decrease tumor-infiltrating Tregs and prevent tumor progression." (PMID 34761735, 2022). "The mutual role played by vascular remodeling and immune activation in dictating the response to immunotherapy in GB has been recently emphasized by the observation that CD4+ lymphocytes are primary actors of the so-called tumor vessel normalization." (PMID 35805021, 2022). "In the TIME, CD4+ T cells are traditionally considered as “helpers” of CD8+ T cells; however, recent studies have shown that a cluster of CD4+ T cells have cytotoxic activity and anti-tumor effects like CD8+ T cells." (PMID 36611881, 2022). "Investigators have recently demonstrated that replenishing the gut microbiome with Akkermansia muciniphila in germ-free mice receiving FMTs from patients responding to immunotherapy promotes CCR9 + CXCR3 + CD4 + T-lymphocyte migration into tumor beds." (PMID 35073876, 2022). "These cells are unique in their expression of MHC-II, which is used to present tumor antigens to CD4+ T cells." (PMID 35223381, 2022). "These human CD4+ tTreg killed EGFRvIII tumor cells in a perforin-dependent, partially GzB-dependent manner." (PMID 35493508, 2022). "GITR is triggered by a GITR ligand or an agonist antibody and activates CD8+ and CD4+ effector T cells, reducing tumor‐infiltrating Treg numbers and resulting in activation of immune responses and tumor cell destruction by effector T cells." (PMID 35674216, 2022). "Upon antigen recognition, the CD4 cells transform transcriptionally, phenotypically, and functionally the TAMs inducing tumor rejection." (PMID 35903540, 2022). "The results showed that the endogenous tumor-reactive CD4+T cell only provided limited role in relieving lung metastasis." (PMID 35784297, 2022). "The inoculation of F. nucleatum into C57BL/6 mice orthotopically implanted with AT3 breast cancer cells resulted in the impaired accumulation of tumor‐infiltrating CD4+ and CD8+ T cells." (PMID 35244982, 2022). "In lung adenocarcinoma (LUAD) and epithelial ovarian cancer (EOC), it has been suggested that BTN3A2 expression was positively correlated with CD4+ T cell, neutrophil, B cell, and macrophage infiltration to the tumor area." (PMID 36362212, 2022). "PD-L2 was also significantly upregulated on the surface of tumour-infiltrating CD4+ T cells and CD8+ T cells compared with the levels in circulation in the treatment-naïve setting (p = 0.001 and p = 0.001)." (PMID 35366537, 2022). "Biopsies revealed increasing numbers of tumor-infiltrating CD4+/CD8+ lymphocytes and persistent low numbers of Foxp3+ cells." (PMID 35864254, 2022). "CCL20 thus allows the recruitment of CCR6+ CD4 immunosuppressive T cells (Th17, Treg) at the tumor site and favors the migration and the metastatic potential of CCR6-expressing cancer cells from diverse types." (PMID 36429101, 2022). "In the immediate tumor environment, neutrophils were shown to directly stimulate anti-tumor responses by presenting antigens to CD4+ T-cells and as well as activating cytotoxic CD8+ T-cells." (PMID 35833131, 2022). "With depletion of SHP2 in tumor cells, reduction of CD4+ and induction of CD8+ T cells were observed in both pulmonary tumors and spleens, and the T-cell exhaustion markers were also reduced, matching the effects of systemic SHP2 inhibition." (PMID 36969745, 2022). "Here the authors combine a cytotoxic gene signature from CD4+ and CD8+ T cells with tumor mutational burden to predict immunotherapy response in NSCLC patients, including those with HLA-LOH." (PMID 35831288, 2022).
tumor (continued). "Studies have shown that “hot tumors” recognize and attack tumors by abundant CD4+ and CD8+ tumor infiltrating lymphocytes, which are generally associated with better prognosis as well as improved response to ICB." (PMID 36110223, 2022). "In the brain mets, an increased proportion of B cells, CD4 T cells, and macrophages were observed in the epithelial compartment when compared to the primary tumor." (PMID 35692807, 2022). "The importance of CD4 responses in anti-tumor immunity was highlighted by the need for CD4 tumor-derived neoepitopes for efficacious immunotherapy." (PMID 36362027, 2022). "Treatments with αPD1 and combined αPD1 + αCTLA4 have previously been shown to substantially increase tumour-infiltrating CD4+ and CD8+ TEM cells." (PMID 36289605, 2022). "Our data suggest that this enhanced antitumor efficacy is a consequence of reduced G‐MDSCs and Tregs within the TIME by Mito‐ATO, and a concomitant increase in functional tumor‐infiltrating cytotoxic CD4+ T cells." (PMID 35243806, 2022). "P-gp expression is also found in pro-tumour M82 macrophages as well as anti-tumour NK-cell and Th17/CD4+T cell subsets, implying that P-gp plays a seemingly contradictory role in tumour immunology." (PMID 35743927, 2022). "Tumours treated with low-dose decitabine also had greater CD4+ and CD8+ PD-1-positive tumour-infiltrating T-lymphocytes in the tumour microenvironment compared to the untreated tumours, suggesting an enhanced response to PD-1 inhibition." (PMID 35073851, 2022). "Foreign antigens and all kinds of innate stimuli are often presented by antigen-presenting cells (APCs) to further direct the development and differentiation of different subsets of CD4+ T cells in tumor." (PMID 35993548, 2022). "Despite multiple challenges using ascending doses of tumor cells, DC prophylactic vaccination results in complete protection due to increased levels of effector CD4 and CD8 T cells as well as high production of pro-inflammatory mediators." (PMID 35492876, 2022). "IL-1 signaling activates innate immune cells and drives polarization of CD4+ T cells towards Th1 and Th17 cells, which initiates an adaptive anti-tumor response." (PMID 35739593, 2022). "Pulsed XRT improved survival via durable tumor-specific memory, and the antitumor effects were largely dependent on CD4+ T cells." (PMID 36275767, 2022). "By contrast, five tumor types (ESCA, KICH, KIRP, THYM, and UCEC) were significantly negatively associated with CD4+ T cells, and only THCA was negatively associated with CD8+ T cells." (PMID 35530327, 2022). "CD8+T cells can secrete lymphokines and recognize the specific antigen on tumor cells so as to directly or indirectly kill tumor cells with the help of CD4+ T cells." (PMID 35694271, 2022). "Together, we have demonstrated that naturally primed tumor-specific CD8+ T cells differentiate into TRMs in TDLNs in a CD4 help-, TGF-β-, and tumor antigen-dependent manner." (PMID 36229613, 2022). "We observed that TC presented with significantly more tumor cells and CAFs than IM, but lower densities of CD4+ T cells, CD8+ T cells, MVD, and others." (PMID 36685566, 2022). "CD8+ T cell epitopes activate CTLs tumor immunity through the antigens cross-presentation pathway, while CD4+ T cells activate helper T cells to maintain the function of CTLs." (PMID 35303904, 2022). "Accordingly, it has been revealed that the percentage of CD4+CD25+Foxp3+ Treg cells is elevated in the tumor micro-environment of the patient with metastatic breast cancer." (PMID 35606804, 2022). "While CD8+ T cells are primarily known for their direct cytotoxic effect on tumor cells, CD4+ T cells mostly aid in anti-tumor immunity in an indirect manner." (PMID 36612283, 2022). "MC38-CEA tumor-bearing mice were depleted separately of CD4+ T cells, CD8+ T cells, NK cells, or all in combination, while simultaneously receiving αTIGIT and bintrafusp alfa." (PMID 36211806, 2022).
tumor (continued). "In GBM-implanted mouse models, the decrease of Tregs led to the proliferation of CD4+ T cells and decreased the levels of secreted immunosuppressive cytokines, resulting in tumor rejection and significantly prolonged mouse survival." (PMID 36466873, 2022). "Given that the amount of CD4+ and/or CD8+ lymphocytes was measured in different units at different localizations, only CD4+/CD8+ ratios were compared between tumor regions." (PMID 35454849, 2022). "We next transfected purified CD4+ lymphocytes, which represent the most typical tumor phenotype in ALK+ ALCL, and were able to express active NPM-ALK protein as early as 6 days post-transfection." (PMID 35246138, 2022). "This is possible because the exosomes facilitate CD4 T cell conversion and boost Treg recruitment to suppress anti-tumor immunity." (PMID 35664698, 2022). "Although CD8+ T cells are considered to be the main driving force of antitumor immunity, CD4+ T cells also play an important role in tumor control." (PMID 35646934, 2022). "When CD4+ T cells were depleted in vivo, tumor growth was accelerated in CD-fed mice compared to that in the IgG group." (PMID 36611881, 2022). "Future experiments should further analyze the tumor antigen specificity and functionality of the CD4 and CD8 T cells to determine if the STING ADC enhances the priming and/or recruitment of T cells in the tumors." (PMID 36442099, 2022). "Infiltrating B cells in a tumor can help CD4+ helper T cells and CD8+ cytotoxic T cells undergo activation and expansion." (PMID 35746487, 2022). "It was also shown that tumour infiltrating CD4+CD8+ T can have a memory phenotype and can promote antitumour immunity." (PMID 36551739, 2022). "Local delivery of RdB/IL12/shVEGF to tumour tissues resulted in massive infiltration of differentiated CD4+ T cells, CD8+ T cells, NK cells, and DCs." (PMID 36140243, 2022). "Altogether, these data show that TAMs capture and present tumor antigens to CD4 T cells at the tumor site, inducing IFNγ production by antigen specific effector T cells." (PMID 35903540, 2022). "T cells can effectively combat tumors by generating immunomodulatory antibodies after immune system activation, while immunotherapy for cancer treatment is based on the activation of tumor-reactive CD4+ and CD8+ T cells." (PMID 36146529, 2022). "Based on a barium enema study, a decrease in tumor size was strongly correlated with the density of CD4(+) T cells (p = 0.0013), as well as the density of CD8(+) T cells (p = 0.0020)." (PMID 35682714, 2022). "Regulatory T cells (Tregs), a subset of CD4+ T cells that maintain immune homeostasis and self-tolerance, are a strong suppressor of tumor-specific T cell responses and are thus an important pro-tumoral component in the immune system." (PMID 36497152, 2022). "On the contrary, tumor-infiltrating Vδ1 T cells promoted tumor development by secreting IL-17 and inhibiting the maturation of CD4/CD8 T cells and DC. γδ T cells have been used in clinical anti-tumor therapy and have achieved good results." (PMID 36483555, 2022). "Tumor cell necrosis caused by TACE increased the release of tumor-associated antigens, recruited DCs and increased CD4+T cells." (PMID 36249023, 2022). "An increased frequency of follicular CD8+ and CD4−CD8− T cells was observed in tumor samples, as well as a decreased percentage of activated follicular CD4+ and γδ+ T cells." (PMID 36551555, 2022). "CD4 + T cells are vital regulatory cells in the immune response and play an essential role in tumor development and progression." (PMID 36618928, 2022). "Cryo-thermal CD4+ T cells directly inhibit the growth of tumor cells via CD4+ T-cell-derived IFN-γ, but the effect of IFN-γ alone seemed modest." (PMID 35874660, 2022). "Several investigators reported the pyroptosis of tumor cells can induce inflammatory response in microenvironment and attracting CD4+ and CD8+T-cell populations." (PMID 36118860, 2022).